G6PD (glucose-6-phosphate dehydrogenase)
Diseases named in the same sentence as G6PD in open-access papers (continued):
Sharing a sentence is not in itself a finding about the gene and the disease.
G6PD deficiency (continued). "The World Health Organisation (WHO) recommends screening for G6PD deficiency before prescribing primaquine with a threshold for prescribing the drug set at 30% G6PD activity, a level amenable to qualitative diagnostics." (PMID 38194420, 2024). "G6PD deficiency can be governed by many types of mutations, and the most common mutation in our study population would be G6PD Mediterranean." (PMID 39336532, 2024). "Among the 3,198 patients with G6PD deficiency, 3,092 cases (2,145 males and 947 females) were detected to have G6PD gene variants." (PMID 39076173, 2024). "These correlations suggest that in individuals with jaundice, lower G6PD levels (indicating G6PD deficiency) are associated with higher levels of systemic inflammation, as measured by NLR and SII." (PMID 39336532, 2024). "G6PD deficiency (G6PDd) is a common human enzyme polymorphism associated with the g6pd gene located on the X chromosome." (PMID 39236082, 2024). "Patients with vivax malaria who have glucose-6-phosphate dehydrogenase (G6PD) deficiency, an inherited enzymopathy, are at risk of drug-induced haemolysis when taking either primaquine or tafenoquine." (PMID 38194420, 2024). "In this context, other studies have reported that overexpression of G6PD evokes an inflammatory response in the adipose tissue of diabetic mice, and conversely, G6PD deficiency reduces diet-induced CCL2 and inflammation of adipose tissue in mice." (PMID 38876306, 2024). "G6PD deficiency is an X-linked hereditary genetic defect due to mutations in the G6PD gene, which cause functional variants with many biochemical and clinical phenotypes." (PMID 39100014, 2024). "The usage of methylene blue is contraindicated in patients with Glucose-6-Phosphate Dehydrogenase (G6PD) deficiency as it increases the risk of haemolytic anaemia." (PMID 39615751, 2024). "G6PD levels were checked prior to initiation and were normal (G6PD levels were checked as TMP-SMX can cause hemolytic anemia in patients with G6PD deficiency)." (PMID 39070456, 2024). "G6PD deficiency is the most common human erythro-enzymopathy caused by inherited mutations in the G6PD gene." (PMID 38308253, 2024). "Glucose-6-phosphate dehydrogenase (G6PD) deficiency is a prevalent genetic disorder affecting approximately 400 million people worldwide." (PMID 38834682, 2024). "The third most common variant is G6PD; c.961G > A (p.Val321Met) causing G6PD deficiency, with 8.6% (55/640) and 3.4% (55/1642) of all carriers and participants, respectively." (PMID 38167091, 2024). "Among 7 cases with G6PD mutation abnormalities, 1 female infant with heterozygous mutations displayed a normal phenotype, while the remaining 6 male infants exhibited glucose-6-phosphate dehydrogenase deficiency." (PMID 38561707, 2024). "Of 215 potential subjects (either identified through hospital records or screened at the walk-in clinic for G6PD deficiency), 27 male hemizygote G6PD-deficient volunteers were enrolled to the two studies between November 2018 and August 2022." (PMID 38319064, 2024). "Globally, the G6PD trait, G6PD deficiency and sickle cell trait were the most common subtypes of inherited anemias, which accounted for more than 80% of inherited anemias incident cases, followed by thalassemias trait and sickle cell disorder." (PMID 38079097, 2024). "These mutations lead to decreased activity and stability of the G6PD enzyme, triggering oxidative injury in RBCs and a variety of clinical symptoms known as G6PD deficiency." (PMID 39684266, 2024). "In Brazil, TFQ was incorporated into the SUS in 2023, along with G6PD deficiency tests to be prescribed only to people over 16 years old and with at least 70% G6PD activity." (PMID 39203521, 2024). "Comparison of ROC curves of G6PD activity in predicting G6PD deficiency between different seasons of HeFei." (PMID 38496015, 2024). "In our hospital, we maintain a database of G6PD deficiency to provide family education and appropriate follow-up for G6PD-deficient babies." (PMID 38480787, 2024).
G6PD deficiency (continued). "This requirement of G6PD explains why Methylene Blue therapy is ineffective in individuals with G6PD deficiency." (PMID 39224766, 2024). "Comparisons of the G6PD enzyme activity of the top six common genotypes identified in the G6PD deficiency newborns in male and female." (PMID 39076173, 2024). "Comparison of ROC curves of G6PD activity in predicting G6PD deficiency of HeFei, FuYang, and AnQing." (PMID 38496015, 2024). "In our study using 1642 exomes of a Thai population, 39% of Thai individuals carried a PV and an LPV in at least one of 114 genes (113 genes have been recommended by ACMG) plus G6PD, causing G6PD deficiency, which is most common in the Thai population." (PMID 38167091, 2024). "G6PD deficiency is an X-linked disorder; males are either G6PD deficient or have normal G6PD activity, whereas females exhibit a wide range of G6PD deficiency." (PMID 38323802, 2024). "G6PD deficiency is caused by loss-of-function variants in the G6PD gene, which is located on chromosome X at Xq28, contains 13 exons and 12 introns, and follows an X-linked pattern of inheritance." (PMID 39436963, 2024). "Consumption of fava beans in a patient with glucose-6-phosphate dehydrogenase (G6PD) deficiency, also called favism, can lead to a haemolytic crisis." (PMID 39144870, 2024). "Based on the evaluation of G6PD enzyme activity and the patient’s previous history of G6PD deficiency, we finally treated the patient with low-dose TMP-SMX combined with caspofungin and provided rigorous medical care to the patient." (PMID 39318598, 2024). "We review these here, and consider the global immunometabolic role of G6PD activity and G6PD deficiency in modulating inflammation and immunopathology." (PMID 38938571, 2024). "Rasburicase, a recombinant urate oxidase, is the primary treatment for hyperuricemia in TLS but poses a risk for methemoglobinemia in patients with glucose 6-phosphate dehydrogenase (G6PD) deficiency." (PMID 39677280, 2024). "Historically, South China was endemic for malaria: since G6PD deficiency imparts a selective advantage against malarial infection, the distribution of G6PD deficiency is closely related to the prevalence of malaria." (PMID 39436963, 2024). "For patients diagnosed to have G6PD deficiency, the first step is to detect the enzyme activity of G6PD, select a suitable medication regimen according to the enzyme activity level, and choose non-oxidizing drugs with accurate efficacy as far as possible." (PMID 39318598, 2024). "As a previous study reported, G6PD gene variants K459M, L463H, A32G, P342S, and Q291K account for approximately 95% of the causative reasons for G6PD deficiency individuals in the Chinese population." (PMID 38496015, 2024). "At 4 months post admission, G6PD deficiency in both patients was confirmed using a qualitative G6PD assay." (PMID 38500232, 2024). "The safety profile of dapsone necessitates careful monitoring, particularly concerning hemolytic anemia and glucose-6-phosphate dehydrogenase (G6PD) deficiency." (PMID 39539906, 2024). "Here, we investigated detailed information on inherited anemias (including thalassemias, thalassemias trait, sickle cell disease, sickle cell trait, G6PD deficiency, and G6PD trait) for the period 1990–2019 from the Global Burden of Disease study." (PMID 38079097, 2024). "Inherited anemias can be categorized into various subtypes, including thalassemias, sickle cell disease, and glucose-6-phosphate dehydrogenase (G6PD) deficiency, due to distinct etiological mechanisms." (PMID 38079097, 2024). "Use of a higher dose of primaquine or tafenoquine should take place after testing for G6PD deficiency to avoid primaquine-induced haemolysis in G6PD-deficient patients." (PMID 38254128, 2024).
G6PD deficiency (continued). "Ascorbic acid, also known as vitamin C, is used as a second-line treatment when methylene blue is unavailable or in cases of hypersensitivity to methylene blue, severe renal impairment, pregnancy, or glucose-6-phosphate dehydrogenase (G6PD) deficiency." (PMID 39328678, 2024). "The STANDARD G6PD test (Biosensor) is a novel point-of-care diagnostic capable of identifying G6PD deficiency prior to treatment." (PMID 39028699, 2024). "Here, we review the role(s) of G6PD activity and the effects of G6PD deficiency on immune system function, in health and disease." (PMID 38938571, 2024). "The data revealed significant regional variations in the prevalence of G6PD deficiency, the spectrum of variants, and the allele frequency of G6PD in China." (PMID 39436963, 2024). "Comparison of ROC curves of G6PD activity in predicting G6PD deficiency between different seasons of AnQing." (PMID 38496015, 2024). "In countries with a high prevalence of G6PD deficiency, G6PD measurement should be included in routine examinations both at the onset of diabetes and for the investigation of mild hyperglycemia." (PMID 38538781, 2024). "Glucose-6-phosphate dehydrogenase (G6PD) deficiency is a common X-linked hereditary disorder in southern China." (PMID 39076173, 2024). "The overall prevalence of G6PD deficiency was 6.13% (25/408) and G6PD intermediate accounted for 15.20% (62/408) of the studied population." (PMID 38308253, 2024). "On the other hand, in a genetic description of Korean patients diagnosed with glucose-6-phosphate dehydrogenase deficiency, the mutant G6PD Kangnam was identified." (PMID 39684266, 2024). "The substantial presence of G6PD deficiency and G6PD trait patients had a significant impact on the disease composition and sex ratio of global inherited anemias." (PMID 38079097, 2024). "For example, red blood cells depend on G6PD for protection against oxidative damage, and hereditary G6PD deficiency leads to hemolytic anemia due to the generation of free radicals." (PMID 39796677, 2024). "The molecular epidemiological characteristics of G6PD deficiency have been extensively studied among Chinese populations, including the relationship between common genotypes and G6PD enzyme activity in homozygous males." (PMID 38834682, 2024). "It is well known that G6PD deficiency is a genetic disorder, with the G6PD gene located on the Xq28 band." (PMID 39726786, 2024). "One of the most widespread enzymopathies affecting human beings is glucose-6-phosphate dehydrogenase (G6PD) deficiency, which is brought on by inherited mutations in the X-linked gene." (PMID 38966448, 2024). "Glucose-6-phosphate dehydrogenase (G6PD) deficiency is an enzymopathy that affects approximately 500 million people worldwide." (PMID 39684266, 2024). "Unfortunately, drugs currently available to treat hypnozoites such as primaquine can cause severe haemolysis when given to patients who have glucose-6-phosphate dehydrogenase (G6PD) deficiency, a common human enzyme polymorphism." (PMID 39236082, 2024). "The fourth prevalence of recessive condition was G6PD deficiency coded by the G6PD gene with the carrier frequency 3.6% and c.961G>A (p.Val321Met) often observed in heterozygous and pathogenic type (42.7%, 5/12)." (PMID 38553482, 2024). "WHO recommends that, where possible, all patients should be tested for G6PD deficiency before commencing primaquine treatment and a daily primaquine regimen should only be administered if the G6PD activity is 30% or higher." (PMID 37748496, 2024). "Although 8-AQ drugs are well-tolerated by most patients they are strong oxidants and can cause acute haemolysis in individuals with the common enzymopathy glucose-6-phosphate dehydrogenase (G6PD) deficiency." (PMID 38687748, 2024). "This study encompassed a range of diseases, including thalassemias, thalassemias trait, sickle cell disease, sickle cell trait, G6PD deficiency, and G6PD trait." (PMID 38079097, 2024).
G6PD deficiency (continued). "The humanized mouse model of G6PD deficiency is the industry standard for assessing the hemolytic anemia potential of 8-AQs owing to the use of fresh human RBCs (huRBCs) from G6PD-deficient donors." (PMID 38640243, 2024). "Among males, the most prevalent inherited anemia is G6PD deficiency, whereas G6PD trait prevails among females." (PMID 38079097, 2024). "Several studies have indicated that G6PD deficiency is associated with an increased risk of cardiovascular disease, suggesting a potential regulatory role of G6PD in VSMCs." (PMID 38589823, 2024). "This case report underscores the complex relationship between diabetic ketoacidosis (DKA), glucose-6-phosphate dehydrogenase (G6PD) deficiency, and methemoglobinemia." (PMID 38966448, 2024). "In clinical practice, given the relatively high prevalence of G6PD deficiency in this population, G6PD screening for all local newborns is required." (PMID 37492600, 2023). "G6PD mutations have been shown to be linked with G6PD deficiency by causing structural destabilization." (PMID 38066190, 2023). "Seeking G6PD information from healthcare professionals is linked to a higher G6PD deficiency likelihood in these regions, especially among parents aged 31-40 with secondary education or higher." (PMID 38229803, 2023). "The patient was born to parents of Chinese ethnicity and had an unremarkable past medical history except for glucose-6-phosphate dehydrogenase (G6PD) deficiency, which had been diagnosed on routine military medical screening." (PMID 36509054, 2023). "Hemoglobin, hematocrit, ABO group, Rhesus factor, glucose-6-phosphate dehydrogenase (G6PD) deficiency, Hemoglobin S (HbS), and malaria were assessed in mothers and newborns." (PMID 37669757, 2023). "Our study’s findings on the higher proportion of males in the G6PD deficiency patients’ group and in the G6PD with COVID-19 patients’ group are consistent with previous research showing a higher prevalence of G6PD deficiency among males than females." (PMID 37376524, 2023). "A large number of participants (369; 80.4%) believed that G6PD is an inherited disorder with 234 (50.9%) participants, stating that both parents must be carriers to have a child with G6PD deficiency anemia." (PMID 38125694, 2023). "The prevalence of G6PD deficiency was 25%, 33.8% of the males were G6PD deficient, compared to 13.2% of females." (PMID 37892786, 2023). "A total of 65 blood samples from jaundiced infants with G6PD deficiency were analyzed for G6PD genotypes using reverse dot hybridization." (PMID 37492600, 2023). "Because of the high prevalence of the disease in the world and the paucity of research in Saudi Arabia about G6PD deficiency, the idea of examining and assessing the awareness and knowledge of parents who have children affected with G6PD emerged." (PMID 38125694, 2023). "Although G6PD deficiency has been considered a rare disease in Korea, the importance of G6PD testing in various medical conditions has been emphasized due to the increasing number of immigrants and international marriages." (PMID 37176619, 2023). "POC tests for G6PD deficiency include both qualitative rapid tests, as well as quantitative biosensor tests that provide numeric results of patients’ G6PD activity levels." (PMID 37824592, 2023). "The large population in the present study provides representative data for G6PD activity testing in Korea and helps to understand the current use status and disease burden of G6PD deficiency in Korea." (PMID 37176619, 2023). "When notified of a positive NBS for G6PD deficiency, ordering providers are directed to order several diagnostic tests including G6PD quantitative testing and a bilirubin assessment, as well as to make a referral to a pediatric hematologist." (PMID 37092512, 2023). "Among the indications for newborns to be admitted to the NICU, transient tachypnea was the most common, followed by neonatal jaundice and glucose-6-phosphate dehydrogenase (G6PD) deficiency." (PMID 38106728, 2023).
G6PD deficiency (continued). "G6PD deficiency is a genetic disorder, and the gene responsible for encoding G6PD is found on the X-chromosome long arm." (PMID 37892786, 2023). "The World Health Organization recommends that primaquine should be given once weekly for 8-weeks to patients with Plasmodium vivax malaria and glucose-6-phosphate dehydrogenase (G6PD) deficiency, but data on its antirelapse efficacy and safety are limited." (PMID 37672548, 2023). "Oligomerization is essential for G6PD activity, and the majority of natural G6PD mutations leading to severe G6PD deficiency are clustered around the structural NADP+ binding site, affecting G6PD oligomerization, stability, and activity." (PMID 37798264, 2023). "The general awareness of G6PD had an adjusted odds ratio (adjOR) of 2.9, signifying that parents who were informed about the connection between G6PD inheritance and a child's sex were approximately 2.9 times more likely to have a child with G6PD deficiency." (PMID 38229803, 2023). "The G6PD Akrokorinthos mutation was found in non-hospitalized patients with neonatal jaundice (NNJ), which is one of the clinical manifestations of G6PD deficiency, and 37% of G6PD residual activity was detected." (PMID 37628871, 2023). "Glucose 6-phosphate dehydrogenase (G6PD) deficiency is an inherited metabolic disorder that renders red blood cells susceptible to oxidative damage, resulting in hemolytic anemia." (PMID 37176619, 2023). "Glucose-6-phosphate dehydrogenase (G6PD) deficiency is a common metabolic disorder affecting more than 400 million individuals worldwide." (PMID 37892786, 2023). "Although we are unable to calculate the false negative rate of the assay, the results suggest that the most severe cases of G6PD deficiency were detected as indicated by the results of diagnostic G6PD testing." (PMID 37092512, 2023). "Patients with Glucose 6-Phosphate Dehydrogenase (G6PD) deficiency suffer from severe haemolysis if treated with Dapsone." (PMID 37275959, 2023). "By DNA analysis, people living in Shan State, Myanmar, had a high prevalence of G6PD deficiency, where 17.5% carried the G6PD Mahidol variant, with 11.8% in males and 21.0% in females." (PMID 37127600, 2023). "Hemolytic anemia and methemoglobinemia are known complications in patients with glucose-6-phosphate dehydrogenase (G6PD) deficiency." (PMID 36938163, 2023). "Low G6PD activities are collectively called G6PD deficiency and are the key risk factor for 8-aminoquinoline-induced haemolysis." (PMID 36986323, 2023). "The cost effectiveness of implementing G6PD screening with the STANDARD G6PD will vary significantly with heterogeneity in the underlying case burden and severity and the prevalence of G6PD deficiency." (PMID 37242320, 2023). "G6PD deficiency is regarded as a rare disease in Korea, and the assays for G6PD activity have been performed in referral laboratories specialized for those tests." (PMID 37176619, 2023). "The near-patient FINDER digital microfluidic G6PD assay was used to estimate the prevalence of G6PD deficiency in a pediatric African American cohort at Children’s Healthcare of Atlanta." (PMID 38132231, 2023). "The STANDARD G6PD Test enables safe access to drugs which are contraindicated for individuals with G6PD deficiency." (PMID 37824592, 2023). "Almost nine percent (8.9%) of the study participants had G6PD deficiency, and all males were G6PD deficient (100%)." (PMID 37892786, 2023). "This study provides a G6PD enzyme activity reference value for the Myanmar population and further information on the prevalence and variants of G6PD deficiency among the Myanmar population; it also evaluates the feasibility of G6PD deficiency tests." (PMID 37127600, 2023). "In the voluntary Kernicterus Registry in the United States, 20.8% of 125 affected newborns were G6PD-deficient, while the male frequency of G6PD deficiency was estimated to be 0.5%–2.9%." (PMID 37492600, 2023).